NUDCD3 (NudC domain containing 3)
Synonyms: KIAA1068; NudCL
Tractability: Antibody: the Human Protein Atlas places it where antibodies can reach. PROTAC: ubiquitination databases record sites on it; its protein half-life has been measured.
Gene: Protein-coding gene on chromosome 7 (44,379,119 to 44,490,690, reverse strand). Ensembl gene ENSG00000015676.
Subcellular location (Human Protein Atlas): Cytosol; Plasma membrane; Primary cilium; Primary cilium tip; Principal piece
Gene Ontology:
Molecular function: protein binding
Biological process: cilium assembly; protein localization to pericentriolar material
Cellular component: cytoplasmic dynein complex
Genetic constraint (gnomAD): Loss-of-function variants: 12 observed, 39.49 expected, observed/expected ratio (o/e) 0.3, 90% interval 0.19 to 0.49. The upper end of that interval is the gene's LOEUF score, 0.49, which puts it in group 2 of 6, group 1 being the genes least tolerant of losing a copy. Missense variants: 421 observed, 441.14 expected, observed/expected ratio (o/e) 0.95, 90% interval 0.88 to 1.03. Synonymous variants: 166 observed, 169.23 expected, observed/expected ratio (o/e) 0.98, 90% interval 0.86 to 1.12.
Gene-disease validity (ClinGen):
ClinGen rates the evidence that NUDCD3 causes each of these diseases.
severe combined immunodeficiency (autosomal recessive): Limited. Severe combined immunodeficiency (SCID) comprises a group of rare monogenic primary immunodeficiency disorders characterized by a lack of functional peripheral T lymphocytes resulting in early-onset severe respiratory infections and failure to thrive.
Homologues: Orthologues: chimpanzee NUDCD3 (99% identical), rat Nudcd3 (90% identical), guinea pig NUDCD3 (89% identical), mouse Nudcd3 (88% identical), dog NUDCD3 (81% identical), pig NUDCD3 (78% identical), tropical clawed frog nudcd3 (62% identical), zebrafish nudcd3 (55% identical), Drosophila melanogaster CG31251 (27% identical). Paralogues in human: NUDC (26% identical), NUDCD2 (11% identical).
Diseases named in the same sentence as NUDCD3 in open-access papers:
NUDCD3 is named in the same sentence as 4 diseases in open-access papers, as found by Europe PMC text mining. Sharing a sentence is not in itself a finding about the gene and the disease. The quoted sentences say what the papers report.
brain tumors (1 paper, 2025). "Interestingly, NUDCD3 is enriched in the nervous system and has been reported to interact with KLHL proteins that are highly expressed in the brain, involved in actin-binding and neuronal development (rather than participating in the UPS), and implicated in neurological conditions and brain tumors." (PMID 40161598, 2025).
NUDCD3 also shares sentences with these, for which no sentence is quoted: coronary heart disease (1 paper); immune deficiency (1); tumor (1).